BRAF (B-Raf proto-oncogene, serine/threonine kinase)
Diseases named in the same sentence as BRAF in open-access papers (continued):
Sharing a sentence is not in itself a finding about the gene and the disease.
prostate carcinoma (79 papers, 2008 to 2026). A carcinoma that arises from epithelial cells of the prostate gland. "Using the mutant-specific primer pair, we detected the BRAF V595E mutation in one prostatic carcinoma sample (PC2) and four urothelial carcinoma tissues (UC1, UC4, UC5, and UC6)." (PMID 39272320, 2024). "BRAF, frequently mutated in prostate cancer is currently studied as a pan-cancer therapeutic target for solid tumors." (PMID 38983753, 2024). "An example of such a mutation is the altered BRAF gene and the resulting changed BRAF protein, which is already known to play a role in urinary bladder and prostatic carcinomas in dogs." (PMID 39591358, 2024). "In conclusion, this study developed a conventional PCR method for detecting the BRAF V595E mutation in urine and prostatic wash fluid, facilitating the diagnosis of canine urothelial carcinoma (UC) and prostatic carcinoma (PC)." (PMID 39272320, 2024). "In dogs, the BRAF mutation (V595E) is common in bladder and prostate cancer and represents a specific diagnostic marker." (PMID 37570213, 2023). "We have developed a simple and highly sensitive detection method for the canine BRAF V595E mutation commonly found in canine urothelial and prostatic carcinoma cells." (PMID 37733700, 2023). "As a result, the combined inhibition of MAPK and AR pathways provides a potential therapeutic effect in BRAF-mutated prostate cancer patients." (PMID 36969009, 2023). "In the field of canine cancer, the most characterised and most frequently tested somatic mutations are c-kit in mast cell tumours and BRAF in bladder and prostate cancer." (PMID 37570213, 2023). "For early detection of canine urothelial and prostatic carcinoma, we intend to develop and commercialize a simple and rapid detection method for the BRAF V595E mutation, a known mutation in this cancer." (PMID 37733700, 2023). "Analysis of publicly available datasets of human prostate cancer showed that BRAF gene alterations (mutation, fusion, or copy number alteration) were found in 4.7%–6.5% and 3%–4% of patients with metastatic and non-metastatic prostate cancer, respectively." (PMID 35131860, 2022). "The BRAF mutation was identified in 64 primary tumours (9.6%) of different origins with various frequencies, with particularly high frequency in prostatic carcinoma (PC) (20/25, 80%) and urothelial carcinoma (30/45, 67%) tissue samples." (PMID 35324835, 2022). "Our findings suggest therapeutic potential for co-inhibition of the MAPK and AR pathways in BRAF-mutated prostate cancers." (PMID 34211036, 2021). "Our findings suggest that activating mutations in BRAF are associated with primary resistance to enzalutamide, though confirmation in a larger cohort of BRAF-mutated prostate cancer patients is needed." (PMID 34211036, 2021). "Although infrequent, prostate cancers harbor BRAF mutations in around 2% of cases 21,22, mostly involving hotspot mutations p.K601E and p.G469A." (PMID 34211036, 2021). "Together, we find that co-inhibition of the AR and MAPK pathway activity is synergistic in prostate cancer cells carrying a BRAF mutation." (PMID 34211036, 2021). "We found that inhibition of BRAF, or downstream MAPK components MEK and ERK, enhanced enzalutamide sensitivity in prostate cancer cells harboring a mutation in the activating kinase domain of the BRAF gene." (PMID 34211036, 2021). "The BRAF is one of the most common mutated gene in prostate cancer which ranks in the 22th by our method while 245th by Diffusion, 35th by Muf_sum, 57th by DriverNet, 42th by DawnRank and forgets by Muf_max." (PMID 31088372, 2019). "A recent study observed significantly high rates of the BRAF V595E mutation (approximately 80%) in canine iUC and prostate cancer." (PMID 29699519, 2018). "A similar difference in the frequency of BRAF mutation also has been reported in prostate cancer samples from Caucasian populations and men of Korean descent." (PMID 23852643, 2013).
prostate carcinoma (continued). "However, it have been shown that prostate cancer-associated SPOP mutations result in aberrant activation of the MAPK/ERK pathway in a BRAF-dependent manner, potentially contributing to the malignant transformation of cancer cells." (PMID 40492122, 2025). "Similarly, recent findings have linked Zn to MAPK signaling and the oncogene BRAF, which is relevant to prostate cancer." (PMID 38398851, 2024). "In conclusion, identifying BRAF mutations from biopsy material offers a valuable opportunity to enhance cancer treatment strategies (BRAF inhibitors) in canine urothelial carcinomas, prostatic carcinomas, and oral squamous cell carcinomas." (PMID 39591358, 2024). "In prostate cancer, BRAF mutations occur at a relatively low frequency (1.54%) and previous studies have suggested that BRAF mutations in prostate cancer might be targetable." (PMID 36275468, 2022). "In our study, we describe two mCRPC patients with tumors harboring a p.K601E BRAF mutation with early disease progression after commencing enzalutamide treatment, indicating potential relevance of these mutations in driving prostate cancer cell growth and enzalutamide resistance." (PMID 34211036, 2021). "However, the rate of mutations in Ras/MEK/ERK pathway in clinical prostate cancer is very low; only up to 7% of clinical samples have activating point mutations of Ras and around 4 % are positive for BRAF, the most common activating mutation of RAF." (PMID 28915623, 2017). "The identification of mutations in the BRAF and SPOP genes through genomic sequencing offers the potential for predicting the response to prostate cancer immunotherapy, assessing prognosis, and targeting therapy." (PMID 40492122, 2025). "Out of 16 BRAF-positive prostatic carcinomas, 2 were tubulopapillary adenocarcinomas, 6 were mixed solid-tubular adenocarcinomas, and 8 were prostatic urethral carcinomas." (PMID 39591358, 2024). "Correspondingly, it was found through performing a kinome-scale CRISPR/Cas9 screen in CWR-R1 prostate cancer cells that an activated BRAF signaling pathway is resistant to enzalutamide." (PMID 36969009, 2023). "Herein, we confirmed that BRAF gene alterations occur in up to 6.5% of human patients with prostate cancer." (PMID 35131860, 2022). "Whereas the clinical significance of BRAF mutations has been demonstrated in various disease settings, it is unclear what proportion of the MAPK alterations found in prostate cancer lead to meaningful activation of the MAPK pathway." (PMID 34211036, 2021). "Through a kinome-centered CRISPR-Cas9 screen in CWR-R1 prostate cancer cells, we identified activated BRAF signaling as a determinant for enzalutamide resistance." (PMID 34211036, 2021). "Clinically, it is unknown whether NR2F1 plays a role in resistance in other BRAF-mutant cancers (e.g., colorectal, thyroid) or dormancy in solid tumors like breast or prostate cancer." (PMID 40955667, 2025). "BRAF alterations have been reported in 3% to 5% of prostate cancers." (PMID 40492122, 2025). "Among these targets, five of them (A2AR/ADORA2A, CSK, CYP24A1, BRDT, and BRAF) have been suggested in recent scientific papers to be related to prostate cancer and all can interact with ligands with known therapeutic advantages against advanced prostate cancer." (PMID 38983753, 2024). "On the other hand, carcinomas of the prostate and bladder with frequent BRAFV595E mutations in dogs rarely have the concurring BRAFV600E mutation in people, indicating that BRAF mutations are specific for certain types of carcinoma and differ between humans and dogs." (PMID 39591358, 2024). "Our findings suggest that co-inhibition of AR and BRAF in BRAF-mutant prostate cancer patients could be particularly effective." (PMID 34211036, 2021). "Together, these data suggest that MAPK inhibition in combination with enzalutamide may be effective in AR-driven prostate cancer cells having an activated MAPK pathway, through an activating BRAF mutation." (PMID 34211036, 2021).
prostate carcinoma (continued). "Recently, BRAF fusions with different partners have been identified in a variety of epithelial tumors, including melanoma, pilocytic astrocytoma, papillary thyroid, rectal and prostate cancers." (PMID 31007851, 2019). "When analyzing pathways associated with colorectal and prostate cancers, we observed that miRNAs targeting both NMT1/2 and MetAP2 genes also regulate the expression of key genes involved in these pathways, including AKT1, GSK3B, BRAF, MAPK and many others." (PMID 29579063, 2018). "Although constitutive activation of RAS-RAF-MAPK pathway occurs in a majority of advanced prostate tumors, the incidence of direct mutations of the upstream activators such as KRAS and BRAF are not commonly found in prostate cancer." (PMID 23852643, 2013). "Hsa-miR-579-3p has previously been shown to be downregulated in exosomes secreted by prostate cancer cells under hypoxic conditions, and is otherwise implicated in tumorigenesis in multiple other cell types via modulation of oncogenic kinase signaling pathways, such as PI3K, BRAF, RAS, and AKT37–40." (PMID 34031488, 2021). "BRAF gain-of-function alteration, RET fusion, and NTRK fusion are rare alterations detected by CGP testing in patients with prostate cancer." (PMID 41158701, 2025). "In prostate cancers, SLC45A3-BRAF and TMPRSS2-BRAF structural rearrangements thus result in activated BRAF kinase activity under the control of AR." (PMID 39018217, 2024). "Inhibition of BRAF or downstream components of MAPK, such as MEK and ERK, ameliorate the enzalutamide sensitivity in prostate cancer cells." (PMID 36969009, 2023). "Given that more than 70% of canine prostate cancers harbor the BRAFV595E mutation, the companion dog model could be a highly relevant platform for comparative cancer research to understand molecular events leading to BRAF mutation and further develop a BRAF-targeted therapy." (PMID 35131860, 2022). "DNA repair pathway, PI3K/AKT/mTOR pathway, BRAF-MAPK and Wnt signaling pathway and activation by glucocorticoid receptors can restore downstream signaling in prostate cancer by alternative proteins." (PMID 34771580, 2021). "Conversely, some lineage-specific genes are seen to serve as 5′ partners across multiple different 3′ genes; for example, TMPRSS2 and SLC45A3 in prostate cancer have been observed as 5′ partners of ERG, ETV1, ETV4, ETV5, BRAF, and ELK4." (PMID 26684754, 2015). "Moreover, miR-145-5p regulates several critical oncogenes including MYC, BRAF, and NRAS, which are known promoters of prostate cancer cell proliferation and clonogenic potential when aberrantly activated." (PMID 38673886, 2024). "The prostate cancer, bladder cancer, non-small lung cancer, and non-cancer-related pathways revealed by KEGG enrichment analysis were mostly due to the high RAS/BRAF mutation rates." (PMID 30545397, 2018). "As an example, in prostate cancer rearrangements occurred between untranslated exon 1 of SLC45A3 (a prostate-specific androgen responsive gene) and exon 8 of BRAF (GenBank GU149303) or between exon 13 of ESRP1 (an epithelial splicing regulatory protein) and exon 6 of RAF1 (GenBank GU149302)." (PMID 25473895, 2015). "Notably, BRAF and CREB3L2 are both in the KEGG pathway for prostate cancer, thus raising the possibility that PLX4720 may also play a role in interfering with CREB3L2 binding to DNA and impacting transcription, possibly in prostate cancer." (PMID 26132924, 2015). "For ETS fusion-negative prostate cancers subtypes, novel gene fusions have also been identified, including SLC45A3:BRAF, ESRP1:RAF1, SLC45A3:BRAF, ESRP1:RAF1, C15orf21:Myc, EPB41:BRAF, and TMEM79:SMG5." (PMID 23957008, 2013).
Langerhans cell histiocytosis (77 papers, 2012 to 2026). Langerhans cell histiocytosis (LCH) is a systemic disease associated with the proliferation and accumulation (usually in granulomas) of Langerhans cells in various tissues. "Oncogene-induced senescence-associated BRAF mutations have been described in Langerhans cell histiocytosis and Erdheim-Chester disease." (PMID 40620437, 2025). "Case reports on pituitary and multisystem langerhans cell histiocytosis: diagnostic delays, BRAF-targeted therapy, and long-term outcomes." (PMID 41189157, 2025). "Langerhans cell histiocytosis (LCH) is a clonal histiocytic neoplasm usually driven by somatic BRAF mutations, resulting in dysregulated MAPK signalling." (PMID 38804700, 2024). "These lesions have different underlying genetic alterations, pointing to the fact that nuclear irregularities can have multiple causative factors like BRAF mutations in Langerhans cell histiocytosis and FOXL1 gene mutation in ovarian granulosa cell tumor." (PMID 37394464, 2023). "BRAF oncogene mutations have been recently identified in Rosai-Dorfman disease (RDD)—a rare non-Langerhans cell histiocytosis." (PMID 36619621, 2022). "BRAF oncogene mutations are a well-established molecular driver and treatment target in other histiocytoses such as Langerhans cell histiocytosis and Erdheim-Chester disease." (PMID 36619621, 2022). "Response to BRAF-targeted therapy has been reported in one patient with mixed RDD and Langerhans cell histiocytosis harboring a BRAF V600E mutation." (PMID 36619621, 2022). "PCR results showed that there were no BRAF-V600E, KRAS, or NRAS mutations in primary intraosseous RDD; only one case with both RDD and Langerhans cell histiocytosis showed BRAF-V600E mutation." (PMID 36185213, 2022). "Somatic mutations in the BRAF gene have been identified in the Langerhans cells of about half of individuals with Langerhans cell histiocytosis." (PMID 33407701, 2021). "As reported by Davies, BRAF oncogene was found mutated also in some specific hematological neoplasms including hairy cell leukemia but also Langerhans cell histiocytosis and Erdheim-Chester disease." (PMID 27738305, 2017). "Recently, it has been proposed a model of pathogenesis of Langerhans cell Histiocytosis in which there is an initial inflammatory condition potentiated by Interleukin 1, continued by mutations of BRAF genes." (PMID 27251410, 2016). "Identification of the activating BRAFV600E mutation in Erdheim-Chester disease (ECD) and Langerhans cell histiocytosis (LCH) cases provided the basis for the treatment with BRAF and/or MEK inhibitors, but additional treatment options are needed." (PMID 26110571, 2015). "In addition to this BRAF mutation, a high prevalence of somatic MAP2K1 mutations has been reported in BRAF V600E–negative Langerhans cell histiocytosis." (PMID 35207181, 2022). "Langerhans Cell Histiocytosis (LCH) is a rare clonal neoplasm derived from macrophage and dendritic lineages primarily occurring in children, with more than 50% of patients having BRAF mutations." (PMID 38203795, 2024). "The identification of V‐raf murine sarcoma viral oncogene homolog B1 (BRAF)V600E mutations has been recommended in patients with Langerhans cell histiocytosis (LCH) with difficult diagnosis and failure of first‐line treatment." (PMID 31441596, 2019). "The most common missense mutation of BRAF (mainly V600E) contributes to the incidence of various cancers, including Langerhans cell histiocytosis (LCH)." (PMID 27094161, 2016). "Histiocytic neoplasms such as Langerhans cell histiocytosis (LCH) and Erdheim–Chester disease (ECD) are characterized by various mutations in the mitogen-activated protein kinase (MAPK) pathway, including BRAF V600E, MAP2K1, and others." (PMID 41562816, 2026). "We report the case of a 30‐year‐old woman diagnosed with BRAF V600E–mutant pulmonary Langerhans cell histiocytosis who was treated with dabrafenib in combination with trametinib." (PMID 40917251, 2025).
Langerhans cell histiocytosis (continued). "Recent studies have shown that somatic mutations that activate the mitogen mitogen-activated protein kinase (MAPK/ERK) pathway are detectable in most patients with Langerhans cell histiocytosis (LCH) and n-LCH, with BRAF being the most commonly mutated." (PMID 40546505, 2025). "Langerhans cell histiocytosis (LCH) represents a neoplasm originating from immature haematopoietic myeloid precursor cells, often associated with the BRAF-V600E mutation." (PMID 41035835, 2025). "Erdheim-Chester disease (ECD) is an ultra-rare non-Langerhans cell histiocytosis characterized by CD68-positive, CD1a/S100-negative histiocytes, frequently associated with BRAF V600E and MAPK pathway mutations." (PMID 41497010, 2025). "The final diagnosis was Langerhans cell histiocytosis of the left proximal femur, unifocal (single bone), BRAF V600D-positive." (PMID 40535388, 2025). "Other studies revealed BRAF (V600E) mutation in a child with both RDD and Langerhans’ cell histiocytosis (LCH), and pathogenic mutation in exon 12 of the BRAF gene in a patient with central nervous system involvement." (PMID 40406258, 2025). "Out of nine patients with Langerhans cell histiocytosis, 44.4% (4/9) exhibited a MAP2K1 mutation, and 44.4% (4/9) exhibited a BRAF mutation." (PMID 37092519, 2023). "The Langerhans cells were reactive to CD1a and BRAF; hence, a diagnosis of carcinosarcoma ex pleomorphic adenoma with Langerhans cell histiocytosis was given." (PMID 37621779, 2023). "Selective BRAF inhibitors such as vemurafenib have become a treatment option in patients with Langerhans cell Histiocytosis (LCH)." (PMID 29774135, 2018). "In some of the histiocytic neoplasms, especially in Langerhans cell histiocytosis and Erdheim‐Chester disease, neoplastic cells often display mutations in genes triggering the MAPK pathway, including mutations in BRAF (most prevalent: V600E), ARAF, MAP2K1, NRAS or KRAS." (PMID 40938275, 2025). "Non-Langerhans cell histiocytosis shares a high incidence similar to that of BRAF V600E mutations, along with genetic alterations in ARAF, MAP2K1, PIK3CA, K/NRAS, and gene fusions involving BRAF, ALK, NTRK1, and ETV3-NCOA2." (PMID 38963520, 2024). "Similarly, in a chronic lymphocytic leukemia (CLL) patient, treatment with PI3Kδ inhibitor led to a switch from lymphocytic leukemia to Langerhans cell histiocytosis (LCH) with acquired BRAF V600E and STK11 mutations, and loss of expression of B-cell lineage markers such as PAX-5." (PMID 34298815, 2021). "MAP2K1, which encodes MEK1, was not analyzed by next-generation sequencing, and mutations in this gene were detected in Langerhans cell histiocytosis in the absence of BRAF mutations." (PMID 28658279, 2017). "Two of the three patients were children (one BRAF mutant; who received second-line chemotherapy) and the third patient was a 45-year-old woman with multifocal and multisystemic BRAF V600E mutant Langerhans cell histiocytosis with multiple bone lesions (Patient HX36)." (PMID 24938183, 2014). "Histiocytic neoplasms such as Langerhans cell histiocytosis (LCH) and Erdheim–Chester disease (ECD) are derived from macrophage/dendritic lineages and known to be enriched for BRAF V600 mutations with frequencies up to 50%." (PMID 38539548, 2024). "Langerhans cell histiocytosis (LCH) is a rare neoplastic disease that occurs in both children and adults, and BRAF V600E is detected in up to 64% of the patients." (PMID 34116682, 2021). "A trial of vemurafenib, a specific inhibitor of mutant BRAF resulted in substantial clinical improvement in three patients with ECD and Langerhans cell histiocytosis offering a novel and effective therapeutic option for these severe disorders." (PMID 25926131, 2015). "BRAF p.T599_V600insEAT, detected in one classical PTC from our cohort, has never been previously reported in thyroid lesions but was identified in a single case of Langerhans cell histiocytosis." (PMID 36835466, 2023).